LINC01036 (long independently transcribed non-coding RNA 1036)
Gene: Long non-coding RNA gene on chromosome 1 (187,070,700 to 187,687,674, forward strand). Ensembl gene ENSG00000230426.
Diseases named in the same sentence as LINC01036 in open-access papers:
LINC01036 is named in the same sentence as 4 diseases in open-access papers, as found by Europe PMC text mining. Sharing a sentence is not in itself a finding about the gene and the disease. The quoted sentences say what the papers report.
cardioembolic stroke (1 paper, 2024). "The risk variants rs528002287 (locus 15q26.3) in PCSK6 and rs148010464 (locus 1q31.1) an intergenic variant in PLA2G4A/LINC01036 for stroke were unique to South Asia, and were found to be associated with cardioembolic stroke and small vessel stroke in South Asians." (PMID 39268810, 2024).
Stroke (1 paper, 2024). Sudden impairment of blood flow to a part of the brain due to occlusion or rupture of an artery to the brain. "South Asia has two unique variants for stroke, rs528002287 and rs148010464, which maps to genes PCSK6 and the intergenic region of PLA2G4A/LINC01036, respectively." (PMID 39268810, 2024).
cancer (1 paper, 2022). A tumor composed of atypical neoplastic, often pleomorphic cells that invade other tissues. "The role of the other three deregulated ncRNAs upon RBPMS knockout—LINC01036 (upregulated), LOC101927789 (downregulated), and LOC105377329 (downregulated)—have not yet been studied in cancer." (PMID 35008958, 2022).
LINC01036 also shares sentences with these, for which no sentence is quoted: small vessel stroke (1 paper).